SETD4 (SET domain containing 4)
Description:
Protein-lysine N-methyltransferase that methylates both histones and non-histone proteins. Via its catalytic activity, regulates many processes, including cell proliferation, cell differentiation, inflammatory response and apoptosis. Regulates the inflammatory response by mediating mono- and dimethylation of 'Lys-4' of histone H3 (H3K4me1 and H3K4me2, respectively), leading to activate the transcription of pro-inflammatory cytokines IL6 and TNF (By similarity). Through the catalysis of TBK1 monomethylation, may regulate virus-induced interferon signaling. TBK1 monomethylation enhances its interaction with MAVS, STING and IRF3, hence promoting antiviral interferon signaling. Also involved in the regulation of stem cell quiescence by catalyzing the trimethylation of 'Lys-20' of histone H4 (H4K20me3), thereby promoting heterochromatin formation. In the brain, epigenetically controls quiescence of neural stem cells for sustaining a protected neural stem cell population and maintaining a stem cell reservoir for neurogenesis (By similarity). Involved in proliferation, migration, paracrine and myogenic differentiation of bone marrow mesenchymal stem cells (BMSCs) (By similarity). Through the catalysis of XRCC5/Ku70 trimethylation, regulates BAX-mediated apoptosis. SETD4-catalyzed XRCC5 methylation results in XRCC5 translocation to the cytoplasm, where it interacts with BAX, sequestering it from the mitochondria, hence preventing BAX-mediated apoptosis.
Synonyms: C21orf18; C21orf27
Tractability: PROTAC: ubiquitination databases record sites on it.
Safety:
Unwanted effects reported when the protein is acted on. In parentheses: how it was acted on, where the effect was seen, and who reports it.
cardiomyopathies (source: ClinPGx)
vomiting (source: ClinPGx)
Gene: Protein-coding gene on chromosome 21 (36,034,534 to 36,079,389, reverse strand). Ensembl gene ENSG00000185917.
Subcellular location: Cytoplasm, cytosol; Nucleus
Subcellular location (Human Protein Atlas): Nuclear speckles
Gene Ontology:
Molecular function: histone H4K20 methyltransferase activity; histone H4K20 monomethyltransferase activity; histone H4K20me methyltransferase activity; protein-lysine N-methyltransferase activity; histone H3K36 methyltransferase activity; histone H3K4 methyltransferase activity; histone H3K4 monomethyltransferase activity; transcription coactivator activity; histone methyltransferase activity
Biological process: chromatin remodeling; positive regulation of inflammatory response; positive regulation of interleukin-6 production; positive regulation of transcription by RNA polymerase II; positive regulation of tumor necrosis factor production; regulation of cell proliferation in bone marrow
Cellular component: cytosol; nucleus
Genetic constraint (gnomAD): Loss-of-function variants: 41 observed, 53.53 expected, observed/expected ratio (o/e) 0.77, 90% interval 0.6 to 0.99. The upper end of that interval is the gene's LOEUF score, 0.99, which puts it in group 4 of 6, group 1 being the genes least tolerant of losing a copy. Missense variants: 451 observed, 514.01 expected, observed/expected ratio (o/e) 0.88, 90% interval 0.81 to 0.95. Synonymous variants: 181 observed, 202.65 expected, observed/expected ratio (o/e) 0.89, 90% interval 0.79 to 1.01.
Homologues: Orthologues: chimpanzee SETD4 (99% identical), macaque SETD4 (97% identical), guinea pig SETD4 (85% identical), dog SETD4 (85% identical), rabbit SETD4 (83% identical), pig SETD4 (81% identical), mouse Setd4 (77% identical), rat Setd4 (75% identical), tropical clawed frog setd4 (55% identical), zebrafish setd4 (48% identical), Drosophila melanogaster CG33230 (23% identical), Caenorhabditis elegans set-29 (22% identical). Paralogues in human: SETD3 (19% identical), SETD6 (18% identical).
Diseases named in the same sentence as SETD4 in open-access papers:
SETD4 is named in the same sentence as 52 diseases in open-access papers, as found by Europe PMC text mining. Sharing a sentence is not in itself a finding about the gene and the disease. The quoted sentences say what the papers report.
breast carcinoma (8 papers, 2013 to 2023). "Setd4 encodes for a recently characterized methyltransferase involved in breast cancer cell proliferation." (PMID 30199527, 2018). "SETD4 expression is also associated with the maintenance of quiescent breast cancer stem cells." (PMID 35854936, 2022). "Studies with sample types ranging from Artemia embryos to human breast cancers have demonstrated the evolutionarily conserved mechanism of SETD4-regulated CSC quiescence across different species." (PMID 37274024, 2023). "SET domain-containing protein 4 (SETD4) alters heterochromatin formation to epigenetically regulate CSC quiescence in breast cancer." (PMID 36890838, 2023). "SET domain-containing protein 4 (SETD4) epigenetically regulates cell quiescence in breast cancer stem cells (BCSCs), and SETD4-positive BCSCs are chemoradioresistant." (PMID 37274024, 2023). "Quantitative real-time PCR (qPCR) showed elevated expression levels of SETD4 in several breast cancer cell lines." (PMID 24738023, 2013). "Further work will reinforce the importance of SETD4 as a target for breast cancer therapy and will help elucidate the mechanisms involved in its activity." (PMID 24738023, 2013). "SETD4 knockdown in breast cancer cell lines significantly suppressed their proliferation and delayed the G1/S cell cycle transition without affecting apoptosis." (PMID 24738023, 2013). "In addition, we found that high mRNA levels of SETD4 (p=0.0468, HR=1.92), SETD5 (p=0.00231, HR=2.79), or SETD7 (p=0.0391, HR=1.97) were significantly associated (p<0.05) with shorter survival in breast cancer patients." (PMID 25537518, 2015). "To investigate whether the elevated expression of SETD4 plays a crucial role in the proliferation of breast cancer cells, we tested four different shRNA constructs specific for SETD4 (OriGene, Rockville, MD, USA)." (PMID 24738023, 2013). "SETD4 knockdown significantly suppressed MTT metabolism in breast cancer cells." (PMID 24738023, 2013). "Interestingly, suppression of SETD4 drastically reduced the colony formation of MDA-MB-231 breast cancer cells." (PMID 24738023, 2013). "To assess this correlation, we detected SETD4 protein expression in breast cancer tissues." (PMID 24738023, 2013). "Our previous studies have shown SET domain-containing protein 4 (SETD4) as abundantly expressed in Artemia dormant embryos, and that SETD4-defined quiescent cancer stem cells were resistant to chemoradiotherapy and able to produce a cancer cell population upon activation in breast cancer cells." (PMID 34131249, 2021). "In addition, SETD4-defined quiescent breast cancer stem cells (qBCSCs) were resistant to chemoradiotherapy in vitro, and the expression level of SETD4 was increased after chemotherapy in a xenograft tumor model, indicating that SETD4 may be correlated with chemoresistance." (PMID 37274024, 2023). "Similar to our results for SETD4, EZH2 transcript and protein expression are elevated in breast cancer." (PMID 24738023, 2013). "SETD4 overexpression was confirmed by western blot analysis suggesting a correlation between high expression of SETD4 and a lack of the estrogen receptor (ER) in breast cancer." (PMID 24738023, 2013). "The expression of SETD4 was elevated in the HCC-1954, SKBR-3, MDA-MB 231 and MDA-MB 436 cell lines compared with the control HCC-1954-BL cell line, a lymphoblast cell line isolated from the same individual from who the HCC-1954 breast cancer cells were isolated (p<0.001)." (PMID 24738023, 2013). "Quantitative PCR analysis was used to examine SETD4 mRNA expression in a panel of cells, including the non-tumorigenic line HCC-1954-BL and several breast cancer cells." (PMID 24738023, 2013).
prostate carcinoma (2 papers, 2022 to 2025). A carcinoma that arises from epithelial cells of the prostate gland. "Hitherto, the restricted research has suggested the potential participation of SETD4 in the pathogenesis of diverse cancers, including BC, NSCLC, and prostate cancer." (PMID 39817582, 2025). "According to the TCGA database and two reports, SETD4 was fused with TMPRSS2 and ERG in prostate cancers, with FTCD in invasive ductal carcinoma, with KIAA1958 in serous ovarian cancer and with B4Galt6 in lung squamous cancer." (PMID 35854936, 2022). "Furthermore, RNA interference experiments suggest that downregulation of SETD4 may lead to a greater sensitivity to sorafenib in the HepG2 hepatocellular carcinoma (HCC) cell line, and have an impact on the survival of DU145 androgen‐independent prostate cancer cells." (PMID 39817582, 2025).
adrenocortical carcinoma (1 paper, 2025). "Subsequently, we assessed SETD4 expression across various pathological stages, revealing significant variations across adrenocortical carcinoma (ACC), HNSC, testicular germ cell tumors (TGCT), and LIHC." (PMID 39817582, 2025).
breast tumors (1 paper, 2013). "After confirming the elevated expression of SETD4 in breast tumors and cell lines, we knocked down SETD4 expression in MDA-MB 231 cells using short-hairpin constructs." (PMID 24738023, 2013).
Cerebellar hypoplasia (1 paper, 2023). Cerebellar hypoplasia is a descriptive term implying a cerebellum with a reduced volume, but a normal shape and is stable over time. "Comparing these four models suggests that at least one gene in the region that is trisomic in both Ts1Cje and Ts65Dn mice but is not trisomic in Ts1Rhr mice (Sod1 to Setd4 and Ripk4 to Zbtb21) contributes to cerebellar hypoplasia." (PMID 36995257, 2023).
choriocarcinoma (1 paper, 2022). An aggressive malignant tumor arising from trophoblastic cells. "Most recently, SETD4 mRNA was found to be stabilized by a long noncoding RNA CBR3-AS1 in gestational choriocarcinoma, and the subsequent SETD4 overexpression may be responsible for the tumor growth in CBR3-AS1-expressing tumor." (PMID 35854936, 2022).
chronic pancreatitis (1 paper, 2021). A chronic inflammatory process causing damage and fibrosis of the pancreatic parenchyma. "And masson staining revealed a high fibrotic index both in SETD4-CreERT2;Rosa26mTmG/+ (control mice) and SETD4-CreERT2;Rosa26DTA/+ mice 3 days after induction of chronic pancreatitis." (PMID 34131249, 2021).
colorectal cancer (1 paper, 2025). A primary or metastatic malignant neoplasm that affects the colon or rectum. "The expression of SETD4 was abnormal across a variety of cancer types and the expression of SETD4 in colorectal cancer tissues was verified in clinical specimens." (PMID 39817582, 2025). "According to the HPA database, a high level of SETD4 expression was observed in LIHC and colorectal cancer." (PMID 39817582, 2025). "Results showed that a significant overexpression of SETD4 mRNA was observed in colorectal cancer cells compared to normal tissues." (PMID 39817582, 2025).
diffuse large B-cell lymphoma (1 paper, 2025). "Notably, lymphoid neoplasm Diffuse Large B‐cell lymphoma (DLBC) and Thymoma (THYM) showed a heightened SETD4 expression when additional normal samples were included in the analysis." (PMID 39817582, 2025).
glioblastoma multiform (1 paper, 2025). "Conversely, there was a negative correlation between the expression of SETD4 and immune‐related pathways [such as TNFA signaling via NFKB, KRAS signaling upregulated, and Interferon Gamma (IFN‐γ) response] in BLCA, CHOL, and glioblastoma multiform (GBM)." (PMID 39817582, 2025).
infarction (1 paper, 2021). A localised pathological necrosis of tissue resulting from obstruction of the blood supply usually by a thrombus, an embolus, or vascular torsion. "In myocardial infarction injured mice, Setd4 knock-out resulted in attenuated cardiomyocyte apoptosis, decreased infarction size and improved cardiac function." (PMID 34079011, 2021).
kidney chromophobe (1 paper, 2025). "Conversely, SETD4 downregulation was observed in thyroid carcinoma (THCA) and kidney chromophobe (KICH)." (PMID 39817582, 2025).
lung carcinoma (1 paper, 2023). "If the expression level of SETD4 is associated with postoperative tumor recurrence, then it may serve as a potential biomarker for predicting lung cancer recurrence and metastasis." (PMID 37274024, 2023). "Here, SETD4-positive cells were identified as quiescent lung cancer stem cells (qLCSCs) since they expressed high levels of ALDH1 and CD133 and low levels of Ki67." (PMID 37274024, 2023). "SETD4 is a biomarker of qLCSCs, yet it remains unclear whether SETD4 can predict postoperative recurrence in patients with early-stage lung cancer." (PMID 37274024, 2023). "Consistently, IF analysis in NSCLC patient specimens revealed that approximately 97% of SETD4-positive lung cancer cells lacked a Ki67 signal, suggesting that SETD4-positive cells were maintained in a quiescent state." (PMID 37274024, 2023).
melanoma (1 paper, 2025). A malignant, usually aggressive tumor composed of atypical, neoplastic melanocytes. "However, we tested a series of seven immunotherapy cohorts and found that SETD4 expression was significantly lower in responsive patients in a melanoma data set." (PMID 39817582, 2025). "Among a cohort of patients with advanced melanoma undergoing anti‐CTLA4 and anti‐PD1 therapy, the nonresponsive subgroup showed notable SETD4 upregulation." (PMID 39817582, 2025).
mental retardation (1 paper, 2018). "The most statistically significant association with candidate genes, AGA, DYRK1A, SETD4, and TTC3, was found in mental retardation (adjP = 0.0014)." (PMID 29739397, 2018).
mesothelioma (1 paper, 2025). A usually malignant and aggressive neoplasm of the mesothelium which is often associated with exposure to asbestos. "Additionally, promoter methylation and SETD4 gene expression were negatively correlated, particularly in ACC, TGCT, KIRP, mesothelioma (MESO), and KICH." (PMID 39817582, 2025).
myocardial infarction (1 paper, 2021). Gross necrosis of the myocardium, as a result of interruption of the blood supply to the area, as in coronary thrombosis. "Activation of endogenous quiescent c-Kit+ cells by conditional knock-out of the Setd4 gene in c-Kit+ cells induced an increase in vascular endothelial cells of capillaries during homeostasis and in response to the ischemic injury, which led to efficient mitigation of myocardial infarction." (PMID 34079011, 2021).
nonsmall cell lung cancer (1 paper, 2023). "However, the role of SETD4 in chemoresistance, tumor progression, and prognosis in nonsmall cell lung cancer (NSCLC) patients is unclear." (PMID 37274024, 2023).
ovarian serous cystadenocarcinoma (1 paper, 2025). A malignant serous cystic epithelial neoplasm arising from the ovary. "Specifically, SETD4 correlated positively with immune checkpoint inhibitors in some cancer types, including BLCA, CESC, PAAD, SARC, and UVM, but negatively in ACC, COAD, KICH, LIHC, Ovarian Serous Cystadenocarcinoma (OV), READ, STAD, THCA, and UCEC." (PMID 39817582, 2025).
pancreatic adenocarcinoma (1 paper, 2025). "Furthermore, SETD4 hypomethylation was significantly high in BLCA, KIRP, and uterine corpus endometrial carcinoma (UCEC), with COAD, ESCA, LUSC, and pancreatic adenocarcinoma (PAAD) showing even higher levels." (PMID 39817582, 2025).
pancreatic diseases (1 paper, 2021). "Our findings suggest that activated SETD4+ cells could be used as key targets in clinical treatment for a wide range of pancreatic diseases." (PMID 34131249, 2021).
pancreatitis (1 paper, 2021). Inflammation of the pancreas. "SETD4+ cells generate newborn acinar cells in response to cerulein-induced pancreatitis in acinar compartments." (PMID 34131249, 2021). "We concluded that SETD4+ cells predominantly contribute to pancreatic regeneration by producing proliferative newborn acinar cells in response to cerulein-induced pancreatitis." (PMID 34131249, 2021). "However, differing from the previously noted Dclk1+ quiescent cells, we found that SETD4+ cells not only largely contribute to regeneration in cerulein-induced pancreatitis, but also contribute to pancreas development both in the embryonic and postnatal pancreas." (PMID 34131249, 2021). "Control animals (Cerulein) recovered within 7 days from pancreatic injury while the ablation of SETD4+ cells (TAM + Cerulein) led to the inability to regain pancreatic weight and a decreased pancreatitis score." (PMID 34131249, 2021). "Tunel assay and analyses of histology showed that with the ablation of SETD4+ cells, mice had still failed to repair cerulein induced pancreatitis 7 days after cerulein treatment and began to die after 6 days of cerulein treatment." (PMID 34131249, 2021).
paraganglioma (1 paper, 2025). A benign or malignant neoplasm arising from paraganglia located along the sympathetic or parasympathetic nerves. "Based on the results, there was a positive correlation between SETD4 expression and poor OS in ACC, KIRC, and pheochromocytoma and paraganglioma (PCPG)." (PMID 39817582, 2025).
prostate adenocarcinoma (1 paper, 2025). "Moreover, SETD4 expression correlated positively with the likelihood of disease progression in prostate adenocarcinoma (PRAD), ACC, LIHC, and uveal melanoma (UVM)." (PMID 39817582, 2025).
sarcoma (1 paper, 2025). A usually aggressive malignant neoplasm of the soft tissue or bone. "Notably, due to the negative correlations observed between SETD4 and various immune cells in some cancer types, BLCA, LUSC, Sarcoma (SARC), SKCM, and UCEC patients with lower SETD4 levels may benefit from immunotherapy." (PMID 39817582, 2025).
T-lymphoma (1 paper, 2022). "While mouse Setd4 knockout delays radiation-induced T-lymphoma formation, elevated SETD4 expression has been observed in some proliferative cancer cells and is associated with a pro-survival potential." (PMID 35854936, 2022).
viral infection (1 paper, 2023). "Virus infection strongly shifted SETD4 from the lightest or heaviest fractions to the middle-molecular weight fractions, also in a ZNF268a-dependent manner." (PMID 37926288, 2023). "Together, we concluded that ZNF268a mediates the recruitment of SETD4 to TBK1 and associated complexes upon viral infection." (PMID 37926288, 2023). "To further examine the function of SETD4 in antiviral innate immunity, we knocked down SETD4 via siRNAs in HEK293T cells and measured ISRE reporter activation by viral infection." (PMID 37926288, 2023). "Together, we conclude that virus infection triggers TBK1-mediated ZNF268a phosphorylation, which subsequently leads to ZNF268a stabilization and recruitment of SETD4 to TBK1, followed by TBK1 mono-methylation, thereby potentiating TBK1 for antiviral immune signaling." (PMID 37926288, 2023).